SPOP (speckle type BTB/POZ protein)
Diseases named in the same sentence as SPOP in open-access papers (continued):
Sharing a sentence is not in itself a finding about the gene and the disease.
tumor (continued). "Importantly, we found SHH and WNT signaling pathway activities were reduced with SPOP downregulation, suggesting that the tumor-promoting function of SPOP stands in activation of the SHH and WNT signaling pathways, which have been shown to be aberrantly activated in ccRCC35,36." (PMID 34021128, 2021). "In addition to SPOP, other cancer driver genes are altered in the subject’s tumor genome." (PMID 33568750, 2021). "Overall, these studies indicate that SPOP might be a potential tumor suppressor in HCC." (PMID 31901237, 2020). "However, whether SPOP functions as a tumor suppressor in GC should be further validated with more studies in the future." (PMID 31901237, 2020). "Taken together, our study identifies a novel mechanism of TGF-β signaling in tumorigenesis through downregulating the expression of SPOP, a potential tumor suppressor, which may lead to the upregulation of NANOG as we previously reported and consequently enhanced stemness in PCa." (PMID 32364525, 2020). "Notably, the tumor suppressor SPOP promotes DAXX degradation in phase-separated droplets." (PMID 31350900, 2019). "Interestingly, tumors derived from endocrine therapy resistant patients (CRPC) were negative for SPAST and SPOP, suggesting loss of these two autoantigens during tumor progression." (PMID 26863016, 2016). "Functional analyses demonstrate that SPOP suppresses LUAD cell migration, proliferation, and in vivo tumor growth." (PMID 42268896, 2026). "Analysis of the cancer-immunity cycle revealed a positive correlation between SPOP and T cell recruitment and activation, particularly in CD8+ and CD4+ T cells, which are essential for anti-tumor immunity." (PMID 40657370, 2025). "SPOP and RIPK1 were substantially overexpressed in tumor tissues, while RIPK3 expression was reduced." (PMID 41122967, 2025). "Conversely, CSN6 antagonizes the ubiquitin ligase activity of SPOP, thereby stabilizing HMGCS1, which in turn activates YAP1 to drive tumor growth." (PMID 40521202, 2025). "Immunohistochemistry results demonstrated a significant decrease in PD‐L1 levels in tumor tissues following MAP treatment and a notable increase in SPOP levels." (PMID 39499771, 2025). "Pancancer analysis suggests that KIRC is the most representative cancer with abnormally high expression of SPOP and RIPK1, so we selected 786-O cells to construct a nude mouse xenograft tumor model." (PMID 41122967, 2025). "We further examined SPOP expression across clinical stages and pathological grades and observed significant differences only in KIRC among the 26 tumor types." (PMID 41122967, 2025). "The tumor suppressor gene speckle-type POZ protein (SPOP), which is an E3 ubiquitin ligase, regulates lipid metabolism by reducing FASN expression and fatty acid synthesis, thereby leading to tumor suppression." (PMID 39944823, 2025). "Mechanistically, SPOP-mediated SENP7 downregulation increases the sumoylation levels of HP1α, leading to gene silencing and promoting cellular senescence, an important tumor suppression mechanism." (PMID 40521202, 2025). "In conclusion, SPOP plays a pivotal oncogenic role in KC, particularly in RCC, by regulating key tumor suppressors and modulating critical cellular processes." (PMID 40521202, 2025). "Therefore, SPOP may perform its tumor-suppressive functions in both the nucleus and the cytoplasm." (PMID 40521202, 2025). "Significantly, knockdown of SPOP leads to spontaneous replication stress and impaired recovery from replication fork stalling through PI3K/mTOR signaling mechanism to promote tumor progression." (PMID 39074086, 2024). "The positive correlations were observed between SPOP expression and infiltration levels of CD4+ T cells and CD8+ T cells, implying the key role of SPOP in regulating tumor microenvironment." (PMID 39074086, 2024).
tumor (continued). "Mechanistically, in PCa the AR regulates target genes that control cell cycle such as SPOP or LRIG or interacts with tumor suppressors." (PMID 38902772, 2024). "Mechanistically, CSN6 antagonizes speckle‐type POZ protein (SPOP) ubiquitin ligase to stabilize HMGCS1, which in turn activates YAP1 to promote tumor growth." (PMID 38308184, 2024). "Similar to the action of SPOP, FBXO22 directly ubiquitinates and degrades PD-L1, thereby increasing the sensitivity of tumor cells to immunotherapeutic agents." (PMID 39315102, 2024). "The results from Ji’s group showed that SPOP expression was downregulated in HCC and also related to tumor size, differentiation, and metastasis." (PMID 37941785, 2023). "Speckle-type POZ protein (SPOP), a Cullin 3-based ubiquitin ligase (CUL3SPOP), acts as a prostate-specific tumor suppressor." (PMID 35252555, 2022). "Our study revealed that SPOP can bind CXCL16 and promote its degradation, resulting in CAFs increasing the spatial distance between immune cells and tumour cells." (PMID 36042498, 2022). "In breast cancer, studies have revealed that SPOP targets substrates such as c-Myc, steroid receptor coactivator 3 (SRC-3) and progesterone receptor (PR), thus functioning as a tumor suppressor." (PMID 36360288, 2022). "Wild-type SPOP can promote the SRC-3 protein and then suppress AR transcriptional activity, thus functioning as a potential tumor suppressor." (PMID 36009418, 2022). "The results in our study suggested that the overexpression of SPOP inhibited malignant behaviors of CRC cells and promoted the anti-tumor immunity in CRC." (PMID 35461336, 2022). "Interestingly, to date, mutations in SPOP have not been found in RCC tumours." (PMID 36474188, 2022). "As a result, we show that SPOP can enhance its own degradation by binding CXCL16 and encouraging the creation of CAFs, increasing the geographical distance between T cells and tumour cells." (PMID 36042498, 2022). "Here, we demonstrate that a well-known tumor suppressor, Suppressor of Fused (SUFU), is downregulated by SPOP." (PMID 34021128, 2021). "As a tumor suppressor, lncRNA ADAMTS9-AS2 inhibits the tumorigenicity of GCSCs by modulating SPOP expression." (PMID 34805143, 2021). "To explore the potential clinical significance of SUFU downregulation by SPOP, we first performed the immunohistochemical staining to evaluate the levels of SPOP and SUFU among 16 different types of cancers, using human tumor tissue microarrays." (PMID 34021128, 2021). "Previously, we found that SUFU was negatively regulated by SPOP–PTEN axis and acted as a tumor suppressor in ccRCC." (PMID 34021128, 2021). "Because SPOP targets various oncogenic substrates (e.g., AR, DEK, TRIM24, NCOA3, BRD2, and BRD4), accumulation of these oncogenic proteins contributes to tumor formation in the prostate." (PMID 33023230, 2020). "For example, peckle-type pox virus and zinc finger (POZ) protein (SPOP), a representative substrate-recognition subunit of the cullin-RING E3 ligase, is known to play a dual role as an oncogene in the cytoplasm but as tumor suppressor in the nucleus." (PMID 33260674, 2020). "Previously we have revealed that SPOP promotes the degradation of SETD2, an important tumor-suppressor in many cancers, through poly-ubiquitination." (PMID 30237511, 2019). "To examine the anti‐tumour role of SPOP on NSCLC, we silenced endogenous SPOP via siRNA and found that knockdown of SPOP promoted A549 cell proliferation, whereas overexpression of SPOP inhibited cell proliferation." (PMID 30407707, 2019). "It is evident that the mRNA level of SPOP, VDR and SETD7 in CRC tissues is lower than in normal adjacent tissues, indicating the tumor suppressive roles of these genes and the poor differentiation of CRC." (PMID 30171794, 2018).
tumor (continued). "Analysis of protein expression within matched pairs of benign prostate tissue and corresponding tumor areas revealed an increased expression of SPAST and STX18 in most tumor samples whereas SPOP expression remained unchanged." (PMID 26863016, 2016). "Similarly, in TAMs, the pathway can dictate polarisation fate: RMPs can promote anti‐tumour M1 polarisation, while in SPOP‐mutant PCa, NC‐STING signalling induces IL‐6 to drive pro‐tumour M2 polarisation." (PMID 41275427, 2025). "To further explore the expression of SPOP in CRC subpopulations, we analyzed a CRC single-cell dataset (EMTAB8107), which revealed that the expression of SPOP was mainly concentrated in myofibroblasts and was relatively low in tumor cell subpopulations." (PMID 41213915, 2025). "Given that SPOP functions as a tumor suppressor and regulates NANOG degradation, restoring or mimicking SPOP activity could prevent NANOG accumulation and its subsequent oncogenic effects, including enhanced proliferation and metastasis." (PMID 40521202, 2025). "The SPOP Y87N mutant disrupts DEK degradation, promoting DEK accumulation and enhancing sphere-forming capacity in prostate epithelial cells, suggesting a role in tumor initiation." (PMID 40521202, 2025). "Consistent with in vitro data, SPOP depletion slightly reduced tumor growth in nude mice but markedly suppressed tumor growth in C57BL/6 mice, suggesting that host T cell immunity is required for SPOP depletion-mediated tumor suppression." (PMID 41148213, 2025). "Inhibiting CSN6 or enhancing SPOP activity could promote HMGCS1 degradation, thereby diminishing YAP1 activation and subsequent tumor growth." (PMID 40521202, 2025). "Moreover, SPOP was positively correlated with CD8+ T cells, CD4+ T cells, B cells, and macrophages and correlated with effector genes of tumor‐infiltrating immune cells." (PMID 39499771, 2025). "Based on these, we propose the hypothesis that M35L mutation possibly exchanges SPOP substrates from oncoproteins (such as GLI2, c-MYC and TRIM24) to tumor suppressors (such as IRF2BP2), therefore reprogramming the tumor properties of SPOP." (PMID 38409107, 2024). "Given that SPOP binds the SBC in IRF2BP2, we next examined whether disruption of the interaction boots IRF2BP2’s anti-tumor activity." (PMID 38409107, 2024). "We found that the expression of SPOP protein in the cytoplasm was significantly downregulated in 83% of ccRCC tumour tissues and upregulated in 88% of adjacent nontumor tissues (P < 0.0001)." (PMID 36474188, 2022). "Therefore, our study provided a novel link between SPOP/CHAF1A axis and tumor autophagy of DLBCL, acting as the basis for finding novel epigenetic targets for DLBCL treatment." (PMID 35773729, 2022). "We then asked if the elevated SPOP levels in the context of forced ΔERG expression have a functional impact on the oncogenic activity of ΔERG in the androgen-independent PC3 cells, in which ERG promotes tumor cell invasion." (PMID 33531470, 2021). "Meanwhile, the other studies showed that SPOP expression and tumor size or metastasis of tumor patients were not statistically significant." (PMID 34838022, 2021). "Due to the many publications and space limitations, we will not describe the tumor suppressive role that SPOP plays by promoting the ubiquitination and degradation of its substrates in PrCa in detail." (PMID 31901237, 2020). "It was reported that SPOP promotes CCRC through degradation of PTEN, a well-known tumor-suppressor." (PMID 30237511, 2019). "SPOP-mediated DAXX degradation is best understood and potentially important for tumor suppression." (PMID 31350900, 2019). "Additionally, SPOP was found to mediate the C/EBPα-regulated suppression of NSCLC cell proliferation, invasion and migration in vitro and tumor growth in vivo." (PMID 30607139, 2018).
tumor (continued). "Furthermore, we evaluated the effects of C/EBPα siRNA on SPOP expression, tumor cell migration and proliferation via MTT and Transwell assays in vitro and tumor growth in vivo." (PMID 30607139, 2018). "Our studies identified a common characteristic genetic profile of benign nodules, mutually exclusive mutation of SPOP, ZNF148 and EZH1 was observed in 24.3% of the adenomatoid nodules but not in matched PTC tumours." (PMID 28580939, 2017). "Measured SPOP autoantibody levels were very low in the corresponding serum sample of this tumor case and we thus were not able to confirm a link between mutant SPOP and occurrence of circulating SPOP autoantibodies." (PMID 26863016, 2016). "In addition to its degradative functions, SPOP also performs tumor-suppressive roles by regulating the non-degradative ubiquitination of certain substrates, such as inverted formin 2 (INF2) and myeloid differentiation primary response protein 88 (MyD88)." (PMID 40483310, 2025). "However, overexpression of SPOP in combination with MAP did not further enhance T cell killing of tumor cells, indicating that MAP mediates tumor cell killing via SPOP in vitro." (PMID 39499771, 2025). "Therefore, it is reasonable to hypothesize that miR-873-5p may serve as a tumor suppressor in GBM with the involvement of HMOX1, HIF1α and SPOP." (PMID 37382594, 2023). "However, the exact role of SPOP in the biological features of RCC and its potential molecular mechanism in RCC tumours remain unclear." (PMID 36474188, 2022). "Based on the incompatibility between the two tumor subtypes, our work enabled the development of specific custom signatures related to AR and ERG transcript that are necessary to drive proliferation and tumorigenesis in the context of ERG-positive and SPOP-mutants tumors." (PMID 33531470, 2021). "In addition, they detected ERG (by IHC) in only one out of 22 SPOP-mutant human tumor samples, leading them to conclude that mutant SPOP was not regulating ERG178." (PMID 30135717, 2018). "In addition, knockdown of SPOP effectively reversed the effects of BCLAF1 knockdown on apoptosis, cell cycle, and secreted cytokines of Jurkat cells, indicating that BCLAF1 partially depended on SPOP to participate in the suppression of the anti-tumor immune microenvironment." (PMID 38340178, 2024). "Furthermore, the level of SPOP was confirmed to be associated with several clinicopathologic parameters, and a decrease in SPOP was considered a predictor of poor prognosis in patients with NSCLC, suggesting that SPOP could be a potential tumor suppressor in LC." (PMID 31901237, 2020). "Although several studies have uncovered the anti-tumor role of SPOP in HCC, the latest paper shows that SPOP protein levels have no changes in human HCC samples." (PMID 38409107, 2024). "As expected, clinically relevant SPOP mutants do not decrease ERG levels, thus potentiating tumor progression." (PMID 38104650, 2024). "Nearly all samples (regardless of tumor or non-tumor), particularly those labeled blue, displayed an inverse correlation between the expression of TWIST1 and SPOP." (PMID 36115849, 2022). "Taken together, our results characterized a negative correlation between SPOP and SUFU in ccRCC, and suggested a potential tumor suppressor role for SUFU in this disease." (PMID 34021128, 2021). "Furthermore, MAP did not enhance T cell‐mediated killing when SPOP was knocked down in RKO cells, whereas overexpression of SPOP or MAP treatment enhanced T cell killing of tumor cells." (PMID 39499771, 2025). "Importantly, the combination of 6b and anti–PD-1 markedly inhibited WT-B16 tumor growth, but not STING-depleted tumors, indicating that 6b’s antitumor effect depends on SPOP/STING signaling." (PMID 41148213, 2025).
cancer (177 papers, 2012 to 2026). A tumor composed of atypical neoplastic, often pleomorphic cells that invade other tissues. "Both mutants support targeted protein degradation in engineered cells, highlighting opportunities to exploit SPOP variants for ligand‐induced protein degradation in cancers harboring these mutations." (PMID 41532714, 2026). "In the present study, we showed that cancer-associated SPOP mutations increased nuclear size by decreasing LMNB2 protein levels." (PMID 40662365, 2025). "The oligomerization and LLPS of SPOP are crucial for its function, and cancer-associated SPOP mutations can disrupt these processes, impairing the function of wild-type SPOP." (PMID 41280670, 2025). "Collectively, our data showed that cancer-associated SPOP mutation increased nuclear volume, likely through direct binding with LMNB2." (PMID 40662365, 2025). "The evolutionary conservation of the MATH domain suggests that mutations in this region are more likely to disrupt SPOP's core function, contributing to the high frequency of these mutations in cancer." (PMID 40521202, 2025). "It is important to note that the specific mutations in the SPOP gene can vary among different cancer types and individual patients." (PMID 40432836, 2025). "Recent studies have shown that mutations or downregulation of SPOP are closely linked to tumorigenesis in various cancers." (PMID 40657370, 2025). "These insights suggest the potential for tailored therapeutic approaches based on SPOP mutation status in these cancers." (PMID 40432836, 2025). "SPOP is linked to oncogenesis through frequent mutations in cancers such as prostate and endometrial cancers." (PMID 40662365, 2025). "In this study, we demonstrated that cancer-associated speckle-type POZ protein (SPOP) mutations enlarged nuclear size by reducing the protein level of lamin B2 (LMNB2), a key nuclear integrity protein." (PMID 40662365, 2025). "This phenomenon highlights the selective pressure on specific domains of SPOP during cancer progression, emphasizing the importance of hotspot mutations while leaving other regions unaltered." (PMID 40432836, 2025). "Growing evidence has clarified the role of SPOP in carcinogenesis, with its expression levels and mutation status varying in a context-dependent manner across human cancers." (PMID 40521202, 2025). "The emerging role of SPOP in phase separation underscores the complex interplay between genetic mutations and biophysical properties in cancer." (PMID 40521202, 2025). "It is observed that there is an accumulation of SPOP substrates into the protein aggregates due to a cancer‐associated mutation in the MATH domain." (PMID 41268324, 2025). "Cancer-associated SPOP mutations increase nuclear size by reducing LMNB2, compromising nuclear envelope integrity and potentially sensitizing tumors to farnesyltransferase inhibitor therapies." (PMID 40662365, 2025). "Physiological evidence from animal models and pathological evidence from human cancer specimens reveal frequent SPOP mutations, which are associated with a worse prognosis in PCa 57,118,119." (PMID 40521202, 2025). "Targeting the SPOP-MyD88-NF-κB axis holds therapeutic potential, particularly in cancers like DLBCL where mutations disrupt this pathway." (PMID 40521202, 2025). "Future trends in cancer therapy are likely to focus on the creation of small molecule inhibitors or activators of SPOP, tailored to specific cancer types and their underlying genetic aberrations." (PMID 40521202, 2025). "Recent studies have shown that SPOP targets SENP7 for degradation during senescence, while cancer-associated SPOP mutants are impaired in this function." (PMID 40521202, 2025). "Copy number alterations: In addition to point mutations, alterations in the copy number of the SPOP gene have been observed in some cancer cases." (PMID 40432836, 2025).